ADGRB2 (adhesion G protein-coupled receptor B2)
Description:
Orphan G protein-coupled receptor involved in cell adhesion and probably in cell-cell interactions. Activates NFAT-signaling pathway, a transcription factor, via the G protein GNAZ. Involved in angiogenesis inhibition (By similarity).
Synonyms: BAI2
Tractability: Antibody: UniProt places it where antibodies can reach, with high confidence; its Gene Ontology location is reachable by antibodies, with high confidence; UniProt predicts a signal peptide or a membrane-spanning region; the Human Protein Atlas places it where antibodies can reach. PROTAC: ubiquitination databases record sites on it; its protein half-life has been measured.
Gene: Protein-coding gene on chromosome 1 (31,727,117 to 31,764,893, reverse strand). Ensembl gene ENSG00000121753.
Subcellular location: Cell membrane; Secreted
Subcellular location (Human Protein Atlas): Plasma membrane
Gene Ontology:
Molecular function: G protein-coupled receptor activity; protein binding; transmembrane signaling receptor activity
Biological process: calcineurin-NFAT signaling cascade; G protein-coupled receptor signaling pathway; peripheral nervous system development; cell surface receptor signaling pathway; negative regulation of angiogenesis
Cellular component: extracellular region; plasma membrane; membrane
Genetic constraint (gnomAD): Loss-of-function variants: 47 observed, 156.32 expected, observed/expected ratio (o/e) 0.3, 90% interval 0.24 to 0.38. The upper end of that interval is the gene's LOEUF score, 0.38, which puts it in group 1 of 6, group 1 being the genes least tolerant of losing a copy. Missense variants: 1,584 observed, 2,061.9 expected, observed/expected ratio (o/e) 0.77, 90% interval 0.74 to 0.8. Synonymous variants: 870 observed, 867.81 expected, observed/expected ratio (o/e) 1, 90% interval 0.95 to 1.06.
Homologues: Orthologues: chimpanzee ADGRB2 (99% identical), macaque ADGRB2 (99% identical), pig ADGRB2 (98% identical), dog ADGRB2 (97% identical), guinea pig ADGRB2 (96% identical), mouse Adgrb2 (95% identical), rat Adgrb2 (95% identical), rabbit ADGRB2 (71% identical), tropical clawed frog adgrb2 (61% identical), zebrafish adgrb2 (25% identical). Paralogues in human: ADGRB3 (47% identical), ADGRB1 (41% identical), ADGRL2 (13% identical), ADGRL1 (12% identical), ADGRL3 (12% identical), ADGRA2 (11% identical), ADGRA3 (11% identical), ADGRG6 (11% identical), ADGRF5 (11% identical), ADGRG4 (11% identical), ADGRE5 (11% identical), ADGRE2 (10% identical), and 30 more.
Diseases named in the same sentence as ADGRB2 in open-access papers:
ADGRB2 is named in the same sentence as 17 diseases in open-access papers, as found by Europe PMC text mining. Sharing a sentence is not in itself a finding about the gene and the disease. The quoted sentences say what the papers report.
developmental delay (2 papers, 2023). "In 2017, a paper was published in Human Mutation describing a missense variant in ADGRB2 in a patient presenting with developmental delay and progressive spastic paraparesis, features shared with identical twins FAM_4_13 and FAM_4_10 harbouring a de novo pLoF in the same gene." (PMID 38132069, 2023).
Xeroderma pigmentosum complementation group A (1 paper, 2019). Xeroderma pigmentosum complementation group A (XPA) is a severe form of xeroderma pigmentosum (XP; see this term), a rare photodermatosis predisposing to skin cancers. "These eQTLs are significantly associated with 4 genes, including ADGRB2 (adhesion G protein-coupled receptor B2), WASF3 (WAS protein family member 3), SPEF2 (sperm flagellar 2), and XPA (xeroderma pigmentosum complementation group A)." (PMID 31039743, 2019).
tumor (2 papers, 2016 to 2021).
ADGRB2 also shares sentences with these, for which no sentence is quoted: cancer (2 papers); lung carcinoma (2); ovarian carcinoma (2); Progressive spastic paraparesis (2); Alzheimer disease (1); attention deficit/hyperactive disorder (1); breast carcinoma (1); cerebral malaria (1); dementia (1); ischemia (1); metabolic syndrome (1); mood disorder (1); psychiatric disorder (1); type 2 diabetes (1).